FAM171B (family with sequence similarity 171 member B)
Synonyms: KIAA1946; FLJ34104
Tractability: Antibody: UniProt predicts a signal peptide or a membrane-spanning region. PROTAC: ubiquitination databases record sites on it; its protein half-life has been measured.
Gene: Protein-coding gene on chromosome 2 (186,694,019 to 186,765,959, forward strand). Ensembl gene ENSG00000144369.
Subcellular location: Cytoplasmic granule; Membrane
Subcellular location (Human Protein Atlas): Mitochondria; Nucleoplasm; Cytosol; Nucleoli
Gene Ontology:
Cellular component: membrane; synapse
Genetic constraint (gnomAD): Loss-of-function variants: 16 observed, 66.3 expected, observed/expected ratio (o/e) 0.24, 90% interval 0.16 to 0.37. The upper end of that interval is the gene's LOEUF score, 0.37, which puts it in group 1 of 6, group 1 being the genes least tolerant of losing a copy. Missense variants: 767 observed, 946.02 expected, observed/expected ratio (o/e) 0.81, 90% interval 0.76 to 0.86. Synonymous variants: 331 observed, 348.06 expected, observed/expected ratio (o/e) 0.95, 90% interval 0.87 to 1.04.
Homologues: Orthologues: chimpanzee FAM171B (99% identical), macaque FAM171B (98% identical), rabbit FAM171B (93% identical), pig FAM171B (92% identical), mouse Fam171b (89% identical), dog FAM171B (88% identical), rat Fam171b (87% identical), guinea pig FAM171B (83% identical), zebrafish fam171b (40% identical). Paralogues in human: FAM171A1 (30% identical), FAM171A2 (27% identical).
Diseases named in the same sentence as FAM171B in open-access papers:
FAM171B is named in the same sentence as 19 diseases in open-access papers, as found by Europe PMC text mining. Sharing a sentence is not in itself a finding about the gene and the disease. The quoted sentences say what the papers report.
bladder cancer (2 papers, 2023 to 2024). "In the present study, we found that FAM171B expression was significantly positively associated with advanced clinicopathological stages and poor survival outcomes in bladder cancer patients." (PMID 37915048, 2023). "In this study, we conducted an analysis to investigate the associations between FAM171B expression and the prognosis and clinicopathological stage of bladder cancer." (PMID 37915048, 2023). "Regarding bladder cancer, RNA sequencing of T24 cells revealed that FAM171B is associated primarily with immune functions, including cytokine activity and the immune response." (PMID 37915048, 2023). "Our present study revealed that high expression of FAM171B is associated with reduced sensitivity to several commonly used chemotherapeutic agents in bladder cancer." (PMID 37915048, 2023). "In conclusion, our findings indicate that FAM171B is associated with the infiltration of M2 macrophages and may serve as a potential prognostic indicator in bladder cancer." (PMID 37915048, 2023). "Therefore, we investigated the impact of FAM171B/CCL2 modulation on bladder cancer-associated macrophage polarization both in vivo and in vitro using double immunofluorescence staining and flow cytometry." (PMID 37915048, 2023). "The effects of FAM171B on modulating tumor-associated macrophages (TAMs) and vimentin-mediated tumor progression, as well as the underlying mechanisms, were clarified by phalloidin staining, immunofluorescence staining, ELISA, RNA immunoprecipitation, flow cytometry and a bladder cancer graft model." (PMID 37915048, 2023). "It has been found that CCL2 overexpression in bladder cancer is due to the FAM171B protein, which can act as an immune regulator and upregulate CCL2 expression." (PMID 38542078, 2024). "Overall, we found a molecular mechanism of CCL2 overexpression in the bladder cancer and showed that treatment targeting FAM171B would be an effective approach for bladder cancer patients with high TAM infiltration." (PMID 37915048, 2023). "The phalloidin staining results demonstrated that efficient overexpression of FAM171B led to morphological changes in bladder cancer cells, which transitioned from an epithelial morphology to a mesenchymal morphology." (PMID 37915048, 2023). "In this study, we revealed that FAM171B promotes bladder cancer progression through its interaction with vimentin, highlighting FAM171B as a critical regulator of cancer metastasis." (PMID 37915048, 2023). "Our study uncovered a novel mechanism for regulating vimentin at the protein level in bladder cancer and partially explains the relationship of FAM171B with poor prognosis in bladder cancer." (PMID 37915048, 2023). "To investigate the role of FAM171B in bladder cancer cells, we conducted RNA sequencing on FAM171B-overexpression and control T24 cells." (PMID 37915048, 2023). "FAM171B significantly promoted bladder cancer growth and metastasis, accompanied by TAM accumulation in the microenvironment in vivo and in vitro." (PMID 37915048, 2023). "Our previous results demonstrated that HNRNPU is an important interacting protein of FAM171B in bladder cancer cells." (PMID 37915048, 2023). "The ELISA results revealed that overexpression of FAM171B increased CCL2 secretion and knockdown of FAM171B decreased CCL2 secretion in MB49 mouse bladder cancer cells." (PMID 37915048, 2023). "We identified vimentin as an important interacting protein of FAM171B in the cytoplasm of bladder cancer cells." (PMID 37915048, 2023). "We identified HNRNPU as another important interacting protein of FAM171B in the nucleus of bladder cancer cells." (PMID 37915048, 2023). "RNA sequencing analysis allowed us to examine the biological function of FAM171B at the transcriptional level in bladder cancer cells." (PMID 37915048, 2023). "In summary, these results confirm that FAM171B contributes to bladder cancer progression by stabilizing vimentin both in vivo and in vitro." (PMID 37915048, 2023).
bladder cancer (continued). "FAM171B expression exhibits strong positive correlation with poor survival outcomes and advanced clinicopathological stages in patients with bladder cancer." (PMID 37915048, 2023). "Beyond its implications in bladder cancer, FAM171B seems to exert substantial immunomodulatory effects in digestive tumors, including colon adenocarcinoma, liver hepatocellular carcinoma, and pancreatic adenocarcinoma." (PMID 37915048, 2023). "To investigate the molecular function of FAM171B in bladder cancer cells, we knocked down and overexpressed FAM171B in T24 and MB49 cells and confirmed the efficiency through Western blot analysis." (PMID 37915048, 2023). "To investigate the impact of FAM171B on drug resistance in bladder cancer, we assessed the predicted chemotherapeutic response using the GDSC dataset." (PMID 37915048, 2023). "Based on our comprehensive findings, FAM171B has great potential as a biomarker for bladder cancer diagnosis and therapeutic interventions." (PMID 37915048, 2023). "To elucidate the molecular role of FAM171B at the protein level, we conducted immunoprecipitation followed by mass spectrometry to identify the major interacting proteins of FAM171B in bladder cancer cells." (PMID 37915048, 2023). "In this study, we identified FAM171B as a potent factor promoting bladder cancer progression that is positively correlated with advanced cancer stages and poor prognosis." (PMID 37915048, 2023). "These in vitro results strongly suggest that FAM171B promotes the malignant phenotype of bladder cancer cells." (PMID 37915048, 2023). "In this study, we identified FAM171B as a potent factor that promotes the progression of bladder cancer." (PMID 37915048, 2023). "To validate the relationships between FAM171B expression and survival rates in bladder cancer, we utilized an integrated cohort of 613 patients from datasets in the GEO database (GSE13507/GSE31684/GSE32894/GSE37815)." (PMID 37915048, 2023). "To assess the clinical significance of FAM171B in bladder cancer, we conducted a comprehensive analysis using data from the TCGA database, the GEO database, and our clinical centre." (PMID 37915048, 2023). "Collectively, these findings highlight vimentin and HNRNPU as the primary interacting proteins of FAM171B in bladder cancer cells." (PMID 37915048, 2023). "Altering the immune microenvironment within tumors by targeting FAM171B could potentially serve as a viable strategy to increase the efficacy of immunotherapy when managing bladder cancer." (PMID 38542078, 2024). "In summary, the results of RNA sequencing provided comprehensive insights into the diverse functions of FAM171B in the T24 human bladder cancer cell line, indicating that its functions primarily involve cytokines, signalling pathway transduction, and cytoskeleton-related processes." (PMID 37915048, 2023). "Previous results demonstrated the interaction between FAM171B and vimentin in bladder cancer cells." (PMID 37915048, 2023). "Furthermore, we aimed to elucidate the impact of FAM171B on bladder cancer cell metastasis using wound healing and transwell invasion." (PMID 37915048, 2023). "However, in our experiments, FAM171B was found to be expressed in both the cytoplasm and the nucleus of human and mouse bladder cancer cell lines." (PMID 37915048, 2023). "Modulating the tumor immune microenvironment by targeting FAM171B may represent a strategy to enhance the effectiveness of immunotherapy in bladder cancer." (PMID 37915048, 2023). "The novel protein family with sequence similarity 171B (FAM171B) has been identified, but its precise role and mechanism in bladder cancer remain unclear." (PMID 37915048, 2023). "Here, we identified FAM171B as a significant factor driving bladder cancer progression." (PMID 37915048, 2023). "Additionally, we used immunoprecipitation and mass spectrometry to identify the protein that interacts with FAM171B in bladder cancer cells." (PMID 37915048, 2023).
bladder cancer (continued). "Therefore, targeting FAM171B constitutes a potentially effective approach for bladder cancer treatment." (PMID 37915048, 2023). "Targeting FAM171B to reduce vimentin levels could offer a promising strategy for preventing metastasis in patients with advanced bladder cancer." (PMID 37915048, 2023). "To investigate whether FAM171B enhances the invasion and migration of bladder cancer cells through vimentin, we conducted wound healing and transwell invasion assays in cells treated with Vimentin-IN-1." (PMID 37915048, 2023). "Additionally, FAM171B was associated with advanced clinicopathological stages in these patients, implying that FAM171B may promote the progression of local invasion and distant metastasis in bladder cancer." (PMID 37915048, 2023). "Our experimental findings demonstrated the impact of FAM171B on both vimentin and the CCL2-CCR2 axis, which significantly influences the progression of bladder cancer." (PMID 37915048, 2023). "To further validate the effect of FAM171B/CCL2 modulation in vivo, we established a mouse subcutaneous transplantation tumor model using MB49 bladder cancer cells." (PMID 37915048, 2023). "To explore the effect of FAM171B and HNRNPU on macrophage chemotaxis, we cocultured RAW264.7 mouse macrophages with different groups of MB49 mouse bladder cancer cells." (PMID 37915048, 2023). "Immunoprecipitation using anti-DYKDDDDK and anti-HA beads confirmed the interactions of FAM171B with vimentin and HNRNPU in MB49 mouse bladder cancer cells." (PMID 37915048, 2023). "We observed positive correlations between FAM171B expression and worse overall survival (OS), progression-free survival (PFS), and disease-specific survival (DSS) outcomes in bladder cancer patients." (PMID 37915048, 2023). "In our western blot analysis using the mouse bladder cancer cell line MB49 and the human bladder cancer cell line T24, we detected two isoforms of FAM171B using this antibody." (PMID 37915048, 2023). "Moreover, we validated the interactions between FAM171B and vimentin/HNRNPU in MB49 bladder cancer cells from mice." (PMID 37915048, 2023). "Therefore, we conducted in vivo and in vitro experiments to investigate the effects of FAM171B and HNRNPU on CCL2 expression in bladder cancer cells." (PMID 37915048, 2023). "However, our experiments did not reveal an association between FAM171B and CAF infiltration in bladder cancer." (PMID 37915048, 2023).
colon cancer (2 papers, 2021 to 2023). "Previous studies have suggested that FAM171B might promote oxaliplatin resistance in colon cancer." (PMID 37915048, 2023).
gastroschisis (2 papers, 2022 to 2023). Gastroschisis is marked by viscera protruding, without a covering sac, from the fetal abdomen on the right lateral base of the umbilicus. "A group of researchers reported on a mutant mouse with gastroschisis that had a mutation in Slit3, as well as an extra point mutation in Fam171A1, a related family member that has 35% amino acid identity with FAM171B." (PMID 36248192, 2022).
attention deficit-hyperactivity disorder (1 paper, 2024). A disorder characterized by a marked pattern of inattention and/or hyperactivity-impulsivity that is inconsistent with developmental level and clearly interferes with functioning in at least two settings (e.g. at home and at school). "For example, male-specific pQTL rs3213946 is also eQTL for several genes (ITGAV, FAM171B, ATP6V1B2 and ZC3H15) and associated with diseases such as inflammatory bowel disease, coronary artery disease, and attention deficit hyperactivity disorder." (PMID 38326779, 2024).
bladder urothelial carcinoma (1 paper, 2023). "The Chronos dependency score revealed that the T24 cell line exhibited the lowest score among the 28 human bladder urothelial carcinoma cell lines in the CCLE database, indicating that FAM171B is more crucial in T24 cells than in the other cell lines." (PMID 37915048, 2023).
congenital heart disease (1 paper, 2023). A heart disease that is present at birth. "FAM171B is an unidentified protein with its function yet to be clearly elucidated, and several studies have suggested its association with a diaphragmatic hernia and congenital heart disease." (PMID 37745050, 2023).
stomach adenocarcinoma (1 paper, 2023). "Notably, pancancer analysis revealed that FAM171B is also linked to poor prognosis in other malignancies, including kidney renal papillary cell carcinoma and stomach adenocarcinoma." (PMID 37915048, 2023).
cancer (2 papers, 2019 to 2023). A tumor composed of atypical neoplastic, often pleomorphic cells that invade other tissues. "Pancancer immune infiltration analysis indicated a positive association between FAM171B and M2 macrophage infiltration in 16 of 33 cancers in the TCGA database." (PMID 37915048, 2023). "Additionally, our pancancer prognostic analysis revealed a correlation between increased FAM171B expression and worse OS in 5 of the 33 cancers in the TCGA database." (PMID 37915048, 2023). "However, despite these insights, our understanding of FAM171B’s structure, function, and specific role in cancer remains limited due to the scarcity of published research on the topic." (PMID 37915048, 2023). "In silico and data-mining analyses suggest that FAM171A1 has been predicted to interact with FAM171B, PCDHGB1, TNFRSF17, TMEM, CTDSPL, and NTRK1, many of which have been already implicated in various cancers suggesting most likely its possible role in the tumorigenesis." (PMID 30631046, 2019). "Further research is needed to explore the comprehensive role of FAM171B and its interaction with HNRNPU in cancer." (PMID 37915048, 2023).
tumor (1 paper, 2023). "Importantly, CCR2 inhibitors also partially reversed the increase in tumor growth and alleviated the weight loss caused by FAM171B overexpression." (PMID 37915048, 2023). "The results of the chemotaxis assays demonstrated that FAM171B overexpression enhanced the chemotaxis of macrophages towards tumor cells in the coculture system, while HNRNPU knockdown and CCR2 inhibition partially attenuated this effect." (PMID 37915048, 2023). "In mouse tumors, overexpression of FAM171B resulted in increases in the tumor volume and mass, while treatment with Vimentin-IN-1 effectively mitigated this effect." (PMID 37915048, 2023). "The results revealed higher expression levels of FAM171B in BLCA tumor tissues than the paired paracancerous tissues." (PMID 37915048, 2023). "Through studies of the molecular mechanism, we found that FAM171B contributes to tumor progression by stabilizing vimentin in the cytoplasm." (PMID 37915048, 2023). "The immunohistochemical analysis and flow cytometry results confirmed that FAM171B overexpression significantly increased macrophage infiltration in tumor tissues and that CCR2 inhibitor treatment effectively suppressed this effect." (PMID 37915048, 2023). "Through studies on the molecular mechanism, we found that FAM171B contributes to tumor progression by stabilizing vimentin in the cytoplasm." (PMID 37915048, 2023). "Moreover, FAM171B enhances CCL2 mRNA splicing by interacting with HNRNPU, ultimately resulted in the recruitment of tumor-associated macrophages (TAMs) and their polarization towards the M2 phenotype." (PMID 37915048, 2023). "Furthermore, FAM171B exerts a stabilizing effect by interacting with vimentin and enhancing its stability, leading to the tumor progression." (PMID 37915048, 2023). "Furthermore, the pancancer immune analysis has revealed that FAM171B plays extensive and important immunomodulatory roles across various tumor types." (PMID 37915048, 2023). "In our study, both bioinformatics and immunofluorescence analyses revealed a negative correlation between FAM171B and CD8 + T cell infiltration, suggesting that FAM171B may exacerbate immunosuppression and facilitate tumor progression." (PMID 37915048, 2023). "Importantly, inhibition of CCR2 partially attenuated FAM171B-induced tumor progression." (PMID 37915048, 2023). "In this study, we found that FAM171B-induced CCL2 modulated the TME by promoting the infiltration and M2 polarization of TAMs, ultimately leading to tumor progression." (PMID 37915048, 2023). "In conclusion, these experiments demonstrate that FAM171B promotes CCL2 secretion via HNRNPU, resulting in macrophage infiltration and tumor progression." (PMID 37915048, 2023).
FAM171B also shares sentences with these, for which no sentence is quoted: pulmonary arterial hypertension (2 papers); colon adenocarcinoma (1); colorectal carcinoma (1); coronary artery disease (1); diaphragmatic hernia (1); digestive tumors (1); inflammatory bowel disease (1); myelomeningocele (1); pancreatic adenocarcinoma (1); Parkinson's (1).